NLRC4 (NLR family CARD domain containing 4)
Description:
Key component of inflammasomes that indirectly senses specific proteins from pathogenic bacteria and fungi and responds by assembling an inflammasome complex that promotes caspase-1 activation, cytokine production and macrophage pyroptosis. The NLRC4 inflammasome is activated as part of the innate immune response to a range of intracellular bacteria (By similarity).
Synonyms: Ipaf; CARD12; CLAN; CLAN1; CLANA; CLANB; CLANC; CLAND; CLR2.1; AIFEC; FCAS4
Tractability: Small molecule: a structure with a bound ligand is known. Antibody: its Gene Ontology location is reachable by antibodies, with high confidence. PROTAC: its protein half-life has been measured.
Gene: Protein-coding gene on chromosome 2 (32,224,453 to 32,265,770, reverse strand). Ensembl gene ENSG00000091106.
Subcellular location: Cytoplasm; Cytoplasm, cytosol; Inflammasome
Subcellular location (Human Protein Atlas): Cytosol; Plasma membrane; Vesicles
Pathways (Reactome):
Immune System: The IPAF inflammasome
Gene Ontology:
Molecular function: ATP binding; caspase binding; endopeptidase activator activity; identical protein binding; protein binding; protein homodimerization activity; magnesium ion binding
Biological process: defense response to bacterium; detection of bacterium; positive regulation of apoptotic process; positive regulation of interleukin-1 beta production; positive regulation of protein processing; activation of innate immune response; icosanoid biosynthetic process; inflammatory response; pattern recognition receptor signaling pathway; positive regulation of inflammatory response; protein homooligomerization; pyroptotic inflammatory response; regulation of apoptotic process
Cellular component: canonical inflammasome complex; cytosol; cytoplasm; IPAF inflammasome complex
Genetic constraint (gnomAD): Loss-of-function variants: 51 observed, 67.91 expected, observed/expected ratio (o/e) 0.75, 90% interval 0.6 to 0.95. The upper end of that interval is the gene's LOEUF score, 0.95, which puts it in group 4 of 6, group 1 being the genes least tolerant of losing a copy. Missense variants: 971 observed, 1,156.5 expected, observed/expected ratio (o/e) 0.84, 90% interval 0.8 to 0.88. Synonymous variants: 419 observed, 443.24 expected, observed/expected ratio (o/e) 0.95, 90% interval 0.87 to 1.02.
Homologues: Orthologues: chimpanzee NLRC4 (99% identical), macaque NLRC4 (95% identical), rat Nlrc4 (76% identical), mouse Nlrc4 (75% identical), guinea pig NLRC4 (65% identical), tropical clawed frog nlrc4 (46% identical), Drosophila melanogaster Diap2 (6% identical), zebrafish birc5b (4% identical), Caenorhabditis elegans bir-2 (3% identical). Paralogues in human: NAIP (18% identical), BIRC6 (14% identical), BIRC2 (8% identical), BIRC3 (7% identical), XIAP (6% identical), BIRC7 (5% identical), BIRC5 (4% identical).
Diseases named in the same sentence as NLRC4 in open-access papers:
NLRC4 is named in the same sentence as 253 diseases in open-access papers, as found by Europe PMC text mining. Sharing a sentence is not in itself a finding about the gene and the disease. The quoted sentences say what the papers report.
macrophage activation syndrome (53 papers, 2014 to 2025). A complication of rheumatic disease that is caused by excessive activation and uncontrolled proliferation of T lymphocytes and well-differentiated macrophages. "While NLRC4’s gain-of-function mutations have been associated with early-onset recurrent fever, recurrent macrophagic activation syndrome and enterocolitis, loss-of-function variants are predicted to be tolerated." (PMID 38927735, 2024). "Consistent with our results in humans, a type I IFN signaling pathway was identified among the top upregulated gene networks in a patient harboring a dominant activating mutation in NLRC4 (T337S), which leads to macrophage activation syndrome." (PMID 38652550, 2024). "Each of these NLRC4 mutations cause severe/recurrent macrophage activation syndrome (MAS)-like episodes characterized by elevated IL-18 serum levels." (PMID 38090573, 2023). "IL-18 production is a hallmark of several monogenic immunodeficiencies that produce IBD symptoms, including macrophage activation syndrome (MAS) secondary to NLRC4 mutation, as well as mutations in X-linked inhibitor of apoptosis (XIAP)." (PMID 36986830, 2023). "Humans with mutations in NLRC4 develops an autoinflammatory syndrome presented with acute fever and feature indicative of Macrophage Activation Syndrome (MAS)." (PMID 35795683, 2022). "Gain-of-function mutations in NLRC4 result in early-onset recurrent fever and macrophage activation syndrome (MAS), neonatal-onset enterocolitis with periodic fever, fatal or near-fatal episodes of autoinflammation, or symptoms resembling those of FCAS." (PMID 34635190, 2021). "One of the characteristics of NLRC4-dysregulated diseases is high serum IL-18, and IL-18 blockade is effective in treating macrophage activation syndrome caused by NLRC4 mutation." (PMID 33178225, 2020). "A NLRC4 missense mutation (i.e., T337S) was discovered in a patient with recurrent macrophage activation syndrome (MAS)." (PMID 33036374, 2020). "In 2014, two independent groups reported that novel and/or de novo GOF mutations in NLRC4 cause autoinflammatory syndromes with distinct features of infantile enteropathy and macrophage activation syndrome (MAS)." (PMID 31456795, 2019). "Reported NLRC4 gene mutations cause recurrent fever flares and macrophage activation syndrome (MAS), neonatal-onset enterocolitis and fatal or near-fatal episodes of autoinflammation." (PMID 28588486, 2017). "The disease was termed Nlrc4-macrophage activation syndrome (Nlrc4-MAS) and shares similarity to mutations in the NLRP3 gene that result in the autoinflammatory disease, neonatal onset multisystem inflammatory disease (NOMID)." (PMID 26635450, 2015). "NLRC4-associated autoinflammatory disease (NLRC4-AID) is an autosomal dominant condition presenting with a range of clinical manifestations which can include macrophage activation syndrome (MAS) and severe enterocolitis." (PMID 34783940, 2022). "For instance, NLRP1 mutations lead to NLRP1-associated Auto-Inflammation with Arthritis and Dyskeratosis (NAIAD) and NLRC4 gain-of-function mutations triggers Syndrome of enterocolitis and Autoinflammation associated with mutation in NLRC4 (SCAN4) or recurrent Macrophage Activation Syndrome (MAS)." (PMID 35563744, 2022). "Tadekinig Alfa, a recombinant human IL-18 binding protein, is being tested in adult onset Still’s disease and in NLRC4 related macrophage activation syndrome (inflammatory diseases associated with high plasma IL-18 levels) (ClinicalTrials.gov Identifier: NCT02398435, NCT03113760)." (PMID 34831246, 2021). "NLRC4 mutations also cause infantile enteritis and macrophage activation syndrome." (PMID 33178225, 2020). "Clinical trials are underway to investigate the treatment of adult-onset Still’s disease and NLRC4-related macrophage activation syndrome (inflammatory diseases associated with high plasma IL-18 levels) using IL-18BP (ClinicalTrials.gov Identifier: NCT 02398435, NCT 03113760)." (PMID 30717382, 2019).
macrophage activation syndrome (continued). "Patients with macrophage activation syndrome or a milder phenotype like FCAS may carry gain of function mutations in the NLRC4 (IPAF; CARD12) gene." (PMID 28421071, 2017). "A child with IBD and macrophage activation syndrome (MAS) caused by an NLR family CARD domain-containing protein 4 (NLRC4) gain-of-function (GOF) gene variant was reported to respond to recombinant human IL-18BP." (PMID 39458007, 2024). "Although the underlying mechanisms of biallelic NLRC4 deficiency remain elusive, IL-18 blockade was shown to be effective in treatment of NLRC4-mediated macrophage activation syndrome indicating that epithelial-derived IL-18 might be a critical pathomechanistic driver." (PMID 36524121, 2022). "A de novo missense mutation (c.1009A > T, encoding p.Thr337Ser) affecting NLRC4 causes early-onset recurrent fever flares and macrophage activation syndrome (MAS)." (PMID 33494299, 2021). "IL-18 is highly elevated in some HLH patients, particularly in cases of XIAP deficiency, patients with NLRC4 mutation, and macrophage activation syndrome (MAS) because of systemic juvenile idiopathic arthritis (sJIA)." (PMID 33442967, 2021). "Activating heterozygous mutations in NLRC4 have been reported to cause recurrent fevers and severe systemic inflammation, similar to macrophage activation syndrome (MAS)." (PMID 30565237, 2019). "Indeed, clinical trials to investigate treatment with IL-18BP for adult-onset Still’s Disease and NLRC4-associated macrophage activation syndrome, inflammatory diseases associated with high plasma IL-18 levels, are ongoing (ClinicalTrials.gov Identifier: NCT 02398435, NCT 03113760)." (PMID 30717382, 2019). "Gain of function (GOF) mutations affecting the inflammasome component NLRC4 are known to cause early-onset macrophage activation syndrome (MAS) and neonatal enterocolitis." (PMID 30319625, 2018). "Several mutations in the nucleotide-binding domain of NLRC4 cause autoinflammatory diseases, early-onset recurrent fever flares, and macrophage activation syndrome (MAS)." (PMID 29259708, 2017). "Inherited or somatic mutations in NLRC4 have also been linked to a spectrum of autoinflammatory disorders, including autoinflammation with infantile enterocolitis (AIFEC) and macrophage activation syndrome (MAS)." (PMID 41087719, 2025). "Studies have indicated that elevated levels of NLRC4 enhance macrophage inflammasome function, potentially contributing to conditions such as infantile small bowel colitis syndrome and recurrent macrophage activation syndrome." (PMID 40028203, 2025). "It has been reported that overexpression of NLRC4 increases macrophage inflammasome activity, leading to infantile small bowel colitis syndrome and recurrent macrophage activation syndrome." (PMID 36765335, 2023). "Two clinical trials evaluated the effect of IL-18 inhibition using IL-18BP in adult-onset Still’s disease and NLRC4-related macrophage activation syndrome (ClinicalTrials.gov Identifier: NCT02398435, NCT03113760)." (PMID 37446301, 2023). "NLRC4-associated autoinflammatory disease (NLRC4-AID) is a recently described autosomal dominant condition presenting with a range of clinical manifestations that can include macrophage activation syndrome (MAS) and severe enterocolitis." (PMID 34783940, 2022). "NLRC4 gain-of-function (GOF) mutations have been associated with early-onset recurrent fever, recurrent macrophagic activation syndrome and enterocolitis." (PMID 34640385, 2021). "Several studies have now identified that mutations in the NLRC4 gene promote a gain of function resulting in the spontaneous inflammasome activation, this causing pediatric enteritis and recurrent macrophage activation syndrome (MAS)." (PMID 34276697, 2021).
macrophage activation syndrome (continued). "IL-18 is a key player in autoinflammatory syndromes, such as familial Mediterranean fever (FMF) caused by pyrin mutations and the Macrophage Activation Syndrome (MAS) caused by NLRC4 gain of function mutations that are characterized by systemically elevated IL-18 levels." (PMID 33101286, 2020). "Hyperactivation of NLRC4 by genetic mutation causes autoinflammatory disorders characterized by CAPS, enterocolitis, or macrophage activation syndrome, which we hereafter call NLRC4-dysregulated diseases." (PMID 33178225, 2020). "In the NLRC4-Macrophage Activation Syndrome (NLRC4-MAS)/Neonatal-Onset Multisystem Inflammatory Disease (NOMID) cohort (GSE57253), the enrichment score of Group 1 was significantly higher in the disease group than in controls (p = 0.04), closely aligning with the clinical pyroptotic state." (PMID 40722833, 2025). "NLRC4-AD is an autosomal dominant autoinflammatory disease caused by mutations in the NLRC4 (NLR family CARD domain-containing protein 4) gene, and encompasses two different phenotypes: NLRC4-associated macrophage activation syndrome (NLRC4-MAS) and familial cold autoinflammatory syndrome 4 (FCAS4)." (PMID 38984133, 2024). "NLRC4 codes for a component of the inflammasome, a cytosolic multiprotein complex that assembles in response to exogenous or endogenous stressors that plays a major role in autoinflammatory diseases, macrophage activation syndrome, and panoptosis." (PMID 35773312, 2022). "In particular, de novo gain-of-function in NLRC4 could be identified in patients presenting with a range of clinical manifestations of autoinflammation and macrophage activation syndrome, including severe very early onset enterocolitis." (PMID 36524121, 2022). "Extremely high levels of IL-18 can be observed in patients affected by NLRC4 inflammasomopathies, or macrophage activation syndrome (MAS)." (PMID 39264518, 2024). "For example, pyrin and NLRP3 are widely expressed in innate immune cells and activate pro-IL-1β, while NLRC4 is expressed in the gut and has pro-IL-18 as substrate, contributing to the development of severe enterocolitis and macrophage activation syndrome (MAS)." (PMID 34198614, 2021).
Salmonella Infections (50 papers, 2013 to 2025). Infections with bacteria of the genus SALMONELLA. "What was observed about NAIPs/NLRC4 inflammasome first is that Salmonella infection in rodents can cause pyroptosis of macrophages in vitro." (PMID 37817895, 2023). "NLRP3 is known to be associated with NLRC4 during Salmonella infection and regulate inflammasome activation." (PMID 30062052, 2018). "YAP phosphorylation is required for downregulation of Nlrc4 in B cells during Salmonella infection; however, the microorganism’s mechanisms underlying the inhibition of the NLRC4 inflammasome in B cells are not fully understood." (PMID 30103648, 2018). "The NLRC4 and NLRP1b inflammasomes are activated by Salmonella infection and anthrax lethal toxin treatment, respectively, resulting in pyroptosis with plasma membrane rupture." (PMID 39550359, 2024). "Along these lines, a recent report has shown that only combined ablation of all the pathways which drive NLRC4 inflammasome-dependent cell death (deletion of Asc, Caspase 1 and Caspase 11, simultaneously) can protect mice from fatal Salmonella infection." (PMID 38236896, 2024). "Although excessive activation of Niap/NLRC4 pyroptosis in intestinal epithelial cells (IECs) contributes to the disruption of the gastrointestinal barrier, this pathway protects mice against Salmonella infection." (PMID 39513865, 2024). "The results revealed that SMI-4a had the inhibitory effect on AIM2 inflammasome and NLRC4 inflammasome, trigged by poly (dA:dT) transfection or Salmonella infection, resulting in a decrease in IL-1β production." (PMID 37422640, 2023). "The NAIP/NLRC4 inflammasome promotes control of intestinal Salmonella infection in mice by triggering pyroptosis and expulsion of infected intestinal epithelial cells." (PMID 35073381, 2022). "The role of NAIP/NLRC4 or other inflammasomes during Salmonella infection of human macrophages is unclear." (PMID 35073381, 2022). "In human THP-1s, Salmonella infection triggers recruitment of both NLRC4 and NLRP3 to the same macromolecular complex, and the NAIP and NLRP3 inflammasomes both contribute to inflammasome responses to Salmonella." (PMID 35073381, 2022). "Altogether, these data indicate that Salmonella infection induces both NAIP/NLRC4- and NLRP3-dependent inflammasome activation in human macrophages, in agreement with previous studies." (PMID 35073381, 2022). "A recent study, which also found that Salmonella infection induces NLRC4- and NLRP3-dependent inflammasome activation in human macrophages, observed that full-length Salmonella flagellin can activate the NLRP3 inflammasome." (PMID 35073381, 2022). "In contrast, Salmonella infection induced activation of inflammasome responses that depended on the collective responses of NAIP/NLRC4, NLRP3, and CASP4/5." (PMID 35073381, 2022). "In this study, we found that while human macrophages require both NAIP and NLRC4 for inflammasome responses to T3SS ligands, NAIP and NLRC4 are only partially required for the inflammasome response during Salmonella infection." (PMID 35073381, 2022). "clarified that activation of the NLRC4 inflammasome in neutrophils during acute Salmonella infection triggered IL-1β maturation, but upon activation of the NLRC4 inflammasome, neutrophils did not go through pyroptosis like macrophages do." (PMID 36059483, 2022). "Salmonella infection induces NAIP/NLRC4-, CASP4/5-, and NLRP3-dependent inflammasome activation in human macrophages." (PMID 35073381, 2022). "Activation of NLRC4 inflammasome by Salmonella infection and AIM2 inflammasome by exposure to poly(dA:dT) resulted in comparable caspase-1 cleavage between WT and Abcb1b–/– cells (data not shown)." (PMID 36038196, 2022). "The phosphorylation of Ser533 is important for NLRC4 activation after Salmonella infection, because it probably drives a conformational change in NLRC4 important for its activation." (PMID 33803783, 2021).